PIGW (phosphatidylinositol glycan anchor biosynthesis class W)
Description:
Acyltransferase that catalyzes the acyl transfer from an acyl-CoA at the 2-OH position of the inositol ring of a 6-(alpha-D-glucosaminyl)-1-(1,2-diacyl-sn-glycero-3-phospho)-1D-myo-inositol (glucosaminyl phosphatidylinositol, GlcN-PI) to generate a 2-acyl-6-alpha-D-glucosaminyl-1-(1,2-diacyl-sn-glycero-3-phospho)-1D-myo-inositol (glucosaminyl acyl phosphatidylinositol, GlcN-(acyl)PI) and participates in the fourth step of GPI-anchor biosynthesis (By similarity). Required for the transport of GPI-anchored proteins to the plasma membrane. Acylation during GPI-anchor biosynthesis is not essential for the subsequent mannosylation and is usually removed soon after the attachment of GPIs to proteins (By similarity).
Synonyms: PIG-W; Gwt1; FLJ37433; HPMRS5
Tractability: Antibody: UniProt predicts a signal peptide or a membrane-spanning region; the Human Protein Atlas places it where antibodies can reach. PROTAC: ubiquitination databases record sites on it; its protein half-life has been measured.
Target class: Enzyme; Transferase
Gene: Protein-coding gene on chromosome 17 (36,534,987 to 36,539,310, forward strand). Ensembl gene ENSG00000277161.
Subcellular location: Endoplasmic reticulum membrane
Subcellular location (Human Protein Atlas): Plasma membrane
Pathways (Reactome):
Metabolism of proteins: Synthesis of glycosylphosphatidylinositol (GPI)
Gene Ontology:
Molecular function: acyltransferase activity, transferring groups other than amino-acyl groups; glucosaminyl-phosphatidylinositol O-acyltransferase activity; acyltransferase activity
Biological process: protein localization to plasma membrane; GPI anchor biosynthetic process; GPI anchor metabolic process
Cellular component: endoplasmic reticulum; endoplasmic reticulum membrane; membrane
Genetic constraint (gnomAD): Loss-of-function variants: 23 observed, 37.02 expected, observed/expected ratio (o/e) 0.62, 90% interval 0.45 to 0.88. The upper end of that interval is the gene's LOEUF score, 0.88, which puts it in group 3 of 6, group 1 being the genes least tolerant of losing a copy. Missense variants: 574 observed, 617.54 expected, observed/expected ratio (o/e) 0.93, 90% interval 0.87 to 1. Synonymous variants: 225 observed, 239.1 expected, observed/expected ratio (o/e) 0.94, 90% interval 0.84 to 1.05.
Gene-disease validity (ClinGen):
ClinGen rates the evidence that PIGW causes each of these diseases.
hyperphosphatasia with intellectual disability syndrome 5 (autosomal recessive): Limited.
Homologues: Orthologues: chimpanzee PIGW (99% identical), macaque PIGW (96% identical), dog PIGW (83% identical), pig PIGW (79% identical), rabbit PIGW (78% identical), guinea pig PIGW (78% identical), rat Znhit3 (76% identical), mouse Pigw (76% identical), tropical clawed frog pigw (45% identical), zebrafish pigw (43% identical), Caenorhabditis elegans pigw-1 (27% identical), Drosophila melanogaster PIG-Wa (22% identical), and 1 more.
Diseases named in the same sentence as PIGW in open-access papers:
PIGW is named in the same sentence as 23 diseases in open-access papers, as found by Europe PMC text mining. Sharing a sentence is not in itself a finding about the gene and the disease. The quoted sentences say what the papers report.
hyperphosphatasia (5 papers, 2017 to 2024). "Mutation of PIGW is associated with West syndrome and hyperphosphatasia with mental retardation syndrome." (PMID 31148949, 2019). "Mutations in six different genes (PIGV, PIGY, PIGO, PGAP2, PIGW, and PGAP3) involved in GPI-anchor biosynthesis have been shown to cause hyperphosphatasia with mental retardation syndrome (HPMRS)." (PMID 29119105, 2017). "Recently, mutations have been identified in six genes (PIGA, PIGY, PIGO, PGAP2, PIGW and PGAP3) encoding proteins in the Glycosyl phosphatidylinositol(GPI)-anchor-synthesis pathway in individuals with hyperphosphatasia with impaired intellectual development syndrome(HPMRS)." (PMID 39687712, 2024). "To date, mutations in six genes (PIGV, PIGY, PIGO, PGAP2, PIGW, and PGAP3) have been shown to cause hyperphosphatasia with mental retardation syndrome (HPMRS) in an autosomal recessive mode of inheritance (no autosomal dominant mutations have been reported thus far)." (PMID 29119105, 2017).
Intellectual disability (4 papers, 2019 to 2022). "So far, variants in PIGW were reported to cause a glycosylphosphatidylinositol biosynthesis defect 11 (OMIM 610275) presenting with developmental delay, intellectual disability, and seizures." (PMID 30679815, 2019). "In contrast, the postnatal cases with variants in PIGW were described clearly in public database to cause a glycosylphosphatidylinositol biosynthesis defect 11 (OMIM 610,275) presenting with developmental delay, intellectual disability, and seizures." (PMID 35227291, 2022). "PIGW (phosphatidylinositol glycan anchor biosynthesis class w protein) and LMX1 (Lim homeobox transcription factor 1, alpha) genes could be associated with mental retardation." (PMID 31149029, 2019).
epilepsy (3 papers, 2019 to 2023). A brain disorder characterized by episodes of abnormally increased neuronal discharge resulting in transient episodes of sensory or motor neurological dysfunction, or psychic dysfunction. "Here, we report an extremely rare case of a Chinese boy with compound heterozygous PIGW mutations who suffers from severe pneumonia, mental retardation, and epilepsy." (PMID 30813920, 2019). "Here, we report a case of HPMRS associated with compound heterozygous mutations in PIGW; the male patient presented with pneumonia, developmental delay, epilepsy, and coarse facial features." (PMID 30813920, 2019).
West syndrome (3 papers, 2019 to 2022). "Compound heterozygous mutations of PIGW have been shown in a patient with mental retardation accompanied by hyperphosphatemia and West syndrome." (PMID 31149029, 2019).
hyperphosphatemia (2 papers, 2019 to 2020). Abnormally high level of phosphate in the blood. "Hyperphosphatemia is a characteristic symptom of some GPI deficiencies, including PIGO, PIGW, PGAP2, etc.." (PMID 32220244, 2020).
congenital disorder of glycosylation (1 paper, 2024). Congenital disorder of glycosylation (CDG) is a fast growing group of inborn errors of metabolism characterized by defective activity of enzymes that participate in glycosylation (modification of proteins and other macromolecules by adding and processing of oligosaccharide side chains). "Glycosylphosphatidylinositol (GPI) biosynthesis defect 11 (GPIBD11), part of the heterogeneous group of congenital disorders of glycosylation, is caused by biallelic pathogenic variants in PIGW." (PMID 39766333, 2024).
Dandy-Walker malformation (1 paper, 2022). "The study also described one homozygous missense variant in gene PIGW which segregated in two sibling fetuses with prenatal Dandy-Walker malformation, hydronephrosis, hypoplastic kidney, genital hypoplasia and diaphragmatic hernia, overlapping with Fryns- or Fryns like syndrome." (PMID 35227291, 2022).
Hypsarrhythmia (1 paper, 2020). Hypsarrhythmia is abnormal interictal high amplitude waves and a background of irregular spikes. "Additionally, hypsarrhythmia EEG was reported in IGDs caused by disease-causing variants in PIGA, PIGP, and PIGW." (PMID 32612635, 2020).
PIGW also shares sentences with these, for which no sentence is quoted: developmental delay (3 papers); Candidemia (2); coccidioidomycosis (2); genetic diseases (2); breast carcinoma (1); Cryptococcal meningitis (1); cryptococcosis (1); deficiencies (1); diaphragmatic hernia (1); hydronephrosis (1); hypophosphatasia (1); infection (1); neurological disorder (1); pneumonia (1); pulmonary aspergillosis (1).